RAB4A (RAB4A, member RAS oncogene family)
Diseases named in the same sentence as RAB4A in open-access papers (continued):
Sharing a sentence is not in itself a finding about the gene and the disease.
cancer (6 papers, 2015 to 2024). A tumor composed of atypical neoplastic, often pleomorphic cells that invade other tissues. "Despite these recent findings, there remains a major gap in knowledge of the molecular mechanisms underlying the roles of RAB4A in cancer." (PMID 39463384, 2024). "RAB4A suppression leads to the loss of cancer cell sphere formation in vitro and loss-of-tumor formation in both subcutaneous and orthotopic xenograft mouse models; this loss of tumorigenesis can be rescued by exogenous expression of constitutively active RAC1 (RAC1CA)." (PMID 39463384, 2024). "RAB4A loss-of-function alone abolished tumor formation in an orthotopic mammary fat pad mice model and reduced sphere formation in serial seeding of cells, indicating the critical involvement of RAB4A in regulating cancer stemness phenotypes that are often associated with EMT." (PMID 36307864, 2022). "RAB4A is involved in the recycling of early endosomes and has been implicated as an important determinant of the invasiveness of cancer cells, thereby providing a possible molecular link between LRIG1 and its apparent metastasis-suppressing function (45, –, 48)." (PMID 29317492, 2018). "To facilitate the studies on the impact of RAB4A, we assayed a group of cancer cell lines for the expression of RAB4A and categorized them into RAB4A-high and RAB4A-low groups." (PMID 39463384, 2024). "So far, we have demonstrated that NUMB, NOTCH1, and RAC1 regulate cancer cell self-renewal downstream of RAB4A, and that this signaling chain controls the transcription of SOX2." (PMID 39463384, 2024). "Relatively, RAB4A is less known for its role in cancer cell signaling; however, several functions have recently emerged in cancer invasiveness and growth." (PMID 39463384, 2024). "The in vitro study of the signaling chain whereby RAB4A impacts cancer cell stemness has demonstrated that NUMB, NOTCH1, RAC1, and SOX2 are essential in mediating the regulatory effects of RAB4A on CSCs in multiple cancer cell lines of diverse tissue origins." (PMID 39463384, 2024). "In conclusion, these studies in both RAB4A-high and RAB4A-low cancer cells demonstrate that RAC1 is upstream of SOX2 in the RAB4A regulation of cancer stemness, while the order of regulation among RAC1, NUMB, and NOTCH1 are yet to be defined." (PMID 39463384, 2024). "In the current study, we have delineated a new signaling circuitry through which RAB4A transmits its control of cancer stemness." (PMID 39463384, 2024). "First, we analyzed RAB4A protein levels in a panel of human cancer cell lines of various tissue origins, which identified RAB4A-high and -low groups." (PMID 36307864, 2022). "We present evidence that RAB4A is a critical regulator of EMT that is the foundation of invasive behavior in many types of human cancer cells." (PMID 36307864, 2022). "This assay result suggests that RAB4A is essential for the self-renewal ability/stemness of the cancer cells that ensures persistent proliferation." (PMID 36307864, 2022). "Mechanistically, this study identifies RAB4A as an upstream regulator of RAC1 activation, through which RAB4A performs these regulatory functions in cancer signaling and major cancer phenotypes." (PMID 36307864, 2022). "Introducing activated RAC1 efficiently rescued EMT gene expression, invasion and tumor formation suppressed by RAB4A knockdown in both the in vitro and in vivo cancer models." (PMID 36307864, 2022). "A major gap in knowledge is the molecular mechanism of RAB4A involvement in cancer initiation and progression." (PMID 36307864, 2022). "In several cancer entities, both, active and inactive β1 receptors are internalized via clathrin- and dynamin-dependent routes to Rab4a-, Rab5-, or Rab21-positive early endosomes." (PMID 33916607, 2021). "We then evaluated the phenotypic impact of NICD in RAB4A regulation of cancer cell stemness." (PMID 39463384, 2024).
cancer (continued). "Overall, this study identified a novel regulatory axis, RAB4A–NUMB–NOTCH1–RAC1 in regulating cancer stemness and tumor initiation and progression and these targets may be further investigated for drug development and cancer therapeutics." (PMID 39463384, 2024). "We have presented evidence that links NUMB to RAB4A regulation for cancer cell stemness, and that loss-of-RAB4A leads to an increased expression of NUMB protein in RAB4A-high cancer cells and exogenous expression of RAB4A in RAB4A-low cells suppresses NUMB protein." (PMID 39463384, 2024). "We then looked at the transcript levels of these genes and found that, consistent with the protein levels, the transcription of Notch1, Sox2, and the stem cell marker Aldh1a3 genes were suppressed, while that of Numb was elevated, in response to RAB4A knockdown in RAB4A-high cancer cells." (PMID 39463384, 2024). "As changes in cancer stemness are associated with the process of EMT, we next assessed the effect of RAC1 rescue in terms of the self-renewal/long term proliferation potential in RAB4A knockdown cells as assessed by serial replating sphere formation assay." (PMID 36307864, 2022). "Consistently, RAB4A suppression abolished the cancer cells’ self-renewal and tumor forming ability." (PMID 36307864, 2022). "However, the question of whether SOX2 is necessary and sufficient in the RAB4A regulation of cancer stemness still needs to be addressed." (PMID 39463384, 2024). "Hence, we speculate that RAB4A likely has immune regulatory function and may impact on tumor microenvironment, a major focus in cancer therapy development for many solid tumors." (PMID 39463384, 2024). "We then validated the levels of NUMB, NOTCH, and SOX2 in a number of RAB4A-high cancer cells (MDA-MB-231, PC3, and SNB19) in response to RAB4A knockdown, and in RAB4A-low cancer cells (MCF7 and H1299) in response to RAB4A over-expression." (PMID 39463384, 2024). "In the previous study, we found RAB4A to be a major upstream regulator of RAC1 activation on EMT and cancer stemness." (PMID 39463384, 2024). "Given its impact on cancer stemness and EMT, we postulate that suppressing RAB4A expression or inhibiting its function would likely halt tumor growth and metastasis, and hence is worthy of future evaluation as a therapeutic target." (PMID 39463384, 2024). "As a regulator of vesicular trafficking, RAB4A may contribute to tumor growth by modulating the transport of various signaling molecules such as growth factors and receptors to the cell surface, thereby affecting cancer cell proliferation and tumor progression." (PMID 39463384, 2024). "In summary, these studies conclude that NOTCH1, through its activation product NICD, forms a necessary link in the RAB4A signaling axis upstream of RAC1 and SOX2 in promoting the cancer cell stemness/self-renewal property." (PMID 39463384, 2024). "As the pathway signatures identified RAB4A as a major upstream stem cell regulator, we next explored the changes in the levels of major cancer-driving proteins in MDA-MB-231 control and RAB4A knockdown cells." (PMID 39463384, 2024). "Using in vitro and in vivo studies, we show that RAB4A, as the upstream regulator, relays signal stepwise to NUMB, NOTCH1, RAC1, and then SOX2 to control the self-renewal property of multiple cancer cells of diverse tissue origins." (PMID 39463384, 2024). "In our recent studies, we found that RAB4A is essential for the continuous proliferation and maintenance of EMT features in cancer cells of multiple tissue origins." (PMID 39463384, 2024). "Phenotypically, in both RAB4A high/NUMB low and RAB4A low/NUMB high cancer cells, NUMB suppresses the long-term sphere formation—a hallmark of cancer stemness." (PMID 39463384, 2024). "This study identifies an involvement of RAB4A, through its regulation of RAC1 activation, in the regulation of EMT, stemness and invasion—all major characteristics of cancer progression, and ultimately patient survival." (PMID 36307864, 2022).
cancer (continued). "Next, we investigated the function of RAB4A in EMT, which is regarded as a critical process in cancer progression and in supporting stemness." (PMID 36307864, 2022). "To evaluate the broader applicability of the newly-discovered relationship between RAB4A and RAC1 in regulating EMT and cell invasion, we expanded the study to other cancer cell lines." (PMID 36307864, 2022). "In this paper, we report a novel signaling cascade of RAB4A–NUMB–NOTCH–RAC1–Sox2 as a major and fundamental driver in promoting cancer stemness and tumorigenesis, significantly extending the mechanistic understanding of the role of RAB4A–RAC1 regulation of EMT and stemness signaling." (PMID 39463384, 2024). "Our recent studies suggest that RAB4A influences the rearrangement of the cytoskeleton, affects the trafficking of integrins and cell adhesion properties, and regulates the EMT process which is considered the common foundation for cancer stemness and metastatic potential." (PMID 39463384, 2024). "The changes in APPL1 (3p21), RAB5A (3p24) and EEA1 (12q22) and RAB4A (1q42) in PIN or primary cancer tissue compared to their expression in non-malignant tissue may discriminate metastatic tissue and provide an avenue for monitoring disease progression." (PMID 26473288, 2015). "The findings confirmed that RAB4A positively controls levels of NOTCH1 and SOX2, and negatively of NUMB, in these cancer cells." (PMID 39463384, 2024). "Although the activation of RAC1 responds to various stimuli, RAB4A has not been previously identified as an upstream regulator for RAC1, particularly in the progression of cancer." (PMID 36307864, 2022).
tumor (4 papers, 2022 to 2025). "In this regard, in our recent study, we also found that expressing activated RAC1 completely restored the sphere formation and tumor formation ability lost due to loss-of-RAB4A." (PMID 39463384, 2024). "RAB4A promotes local invasion and distant metastasis of tumor cell lines, and RAB5A is associated with lymphatic and vascular invasion." (PMID 34350714, 2022). "The work presented in this manuscript describes a step-by-step identification of a novel signaling axis RAB4A–NUMB–NOTCH1–RAC1–SOX2 to elucidate the transmission of signaling downstream from RAB4A to control stemness and tumor formation." (PMID 39463384, 2024). "Knockdown of NUMB, or overexpression of NICD (the active fragment NOTCH1) or SOX2, rescued the in vitro sphere-forming and in vivo tumor-forming abilities that were lost upon RAB4A knockdown." (PMID 39463384, 2024). "Consistent with previous in vivo observation, effective RAB4A knockdown with either of the two shRNAs abolished the tumor-forming ability of MDA-MB-231 cells." (PMID 39463384, 2024). "These in vivo rescue experiments confirm the signaling axis of RAB4A–NUMB–NOTCH–RAC1–SOX2 in the control of stemness/self-renewal that is the foundation for tumor formation." (PMID 39463384, 2024). "Expression of NICD, the nuclear fragment of NOTCH1 that is shown to be downstream of NUMB but also feeds back to NUMB, completely reversed the effect of RAB4A knockdown on the tumor forming ability." (PMID 39463384, 2024). "Among these effects, we have already validated in the in vivo setting that constitutively active RAC1 is able to restore the lost tumor formation ability resulting from RAB4A knockdown." (PMID 39463384, 2024). "The effect of RAB4A KD on tumor formation is likely from RAB4A function on stem cell signaling as we have recently found that RAB4A affects EMT." (PMID 39463384, 2024). "Here, we sought to validate, in a xenograft mouse model, the essential role of NUMB, NOTCH1, and SOX2 in RAB4A-driven tumor formation." (PMID 39463384, 2024). "Specifically, we compared the tumor formation ability of cells derived from MDA‐MB‐231 that expressing either control shRNA or RAB4A shRNA alone or concurrent expression of RAB4A shRNA and either RAC1WT or RAC1CA." (PMID 36307864, 2022). "In the orthotopic mammary fat pad model, we found that efficient RAB4A knockdown completely abolished tumor formation when the cells were implanted in the NOD-SCID mouse mammary fat pad." (PMID 36307864, 2022). "The inability of RAC1WT to restore the tumor formation ability is consistent with the conclusion that RAB4A plays a major role in the activation of RAC1; therefore, only the activated RAC1 can perform the function without the help of RAB4A." (PMID 36307864, 2022). "However, introducing the expression of RAC1CA, but not RAC1WT, restored the tumor formation ability of the RAB4A knockdown cells to the level of control cells, which is consistent with the notion that RAC1 is the primary mediator of RAB4A regulation of tumor formation and progression." (PMID 36307864, 2022). "Taking the RAC1 story further to support its new role as a downstream regulator of RAB4A in EMT, invasion and sphere formation in in vitro settings, we performed an orthotopic in vivo tumor formation study." (PMID 36307864, 2022). "In summary of all the evidence, we illustrate in the in vitro and in vivo settings the essential roles of RAB4A in EMT, cell invasion, stemness and tumor formation." (PMID 36307864, 2022). "To provide more evidence, we have performed some relevant experiments to rule out the potential effects of RAB4A on proliferation and cell death, which can also contribute to tumor formation." (PMID 39463384, 2024). "Interestingly, RAB4A knockdown had no significant growth impact under adherent culturing condition, suggesting that the effect of RAB4A on tumor formation is not through the regulation of short-term proliferation." (PMID 36307864, 2022).
RAB4A also shares sentences with these, for which no sentence is quoted: nephritis (2 papers); diabetes (1); lupus nephritis (1); non-small cell lung carcinoma (1); Obesity (1); psoriasis (1); Thrombocytopenia (1).